MAT2A (methionine adenosyltransferase 2A)
Description:
Catalyzes the formation of S-adenosylmethionine from methionine and ATP. The reaction comprises two steps that are both catalyzed by the same enzyme: formation of S-adenosylmethionine (AdoMet) and triphosphate, and subsequent hydrolysis of the triphosphate.
Synonyms: MAT-II; MATA2; SAMS2; MATII
Tractability: Small molecule: a structure with a bound ligand is known; a high-quality ligand is known; it has a high-quality binding pocket. PROTAC: UniProt records ubiquitination sites on it; ubiquitination databases record sites on it; its protein half-life has been measured; a small molecule that binds it is known.
Target class: Enzyme; Transferase
Chemical probes: AG-270 (high quality), AZ9567 (high quality)
Gene: Protein-coding gene on chromosome 2 (85,539,165 to 85,545,281, forward strand). Ensembl gene ENSG00000168906.
Subcellular location (Human Protein Atlas): Nucleoplasm; Cytosol
Pathways (Reactome):
Metabolism: Methylation
Gene Ontology:
Molecular function: identical protein binding; methionine adenosyltransferase activity; protein binding; small molecule binding; ATP binding
Biological process: cellular response to methionine; positive regulation of TORC1 signaling; protein heterooligomerization; protein hexamerization; S-adenosylmethionine biosynthetic process; protein complex oligomerization
Cellular component: methionine adenosyltransferase complex; nucleus; cytosol
Genetic constraint (gnomAD): Loss-of-function variants: 2 observed, 39.95 expected, observed/expected ratio (o/e) 0.0501, 90% interval 0.019 to 0.16. The upper end of that interval is the gene's LOEUF score, 0.16, which puts it in group 1 of 6, group 1 being the genes least tolerant of losing a copy. Missense variants: 193 observed, 471.02 expected, observed/expected ratio (o/e) 0.41, 90% interval 0.36 to 0.46. Synonymous variants: 191 observed, 162.52 expected, observed/expected ratio (o/e) 1.18, 90% interval 1.04 to 1.33.
Gene-disease validity (ClinGen):
ClinGen rates the evidence that MAT2A causes each of these diseases.
familial thoracic aortic aneurysm and aortic dissection (autosomal dominant): Limited. A rare genetic vascular disease characterized by the familial occurrence of thoracic aortic aneurysm, dissection or dilatation affecting one or more aortic segments (aortic root, ascending aorta, arch or descending aorta) in the absence of any other associated disease.
Homologues: Orthologues: chimpanzee MAT2A (100% identical), mouse Mat2a (99% identical), guinea pig MAT2A (98% identical), macaque MAT2A (97% identical), dog MAT2A (97% identical), pig MAT2A (96% identical), rat Mat2al1 (93% identical), tropical clawed frog mat2a (93% identical), rat Mat2a (92% identical), rabbit MAT2A (92% identical), zebrafish mat2aa (92% identical), zebrafish mat2ab (83% identical), and 5 more. Paralogues in human: MAT1A (84% identical).
Diseases named in the same sentence as MAT2A in open-access papers:
MAT2A is named in the same sentence as 104 diseases in open-access papers, as found by Europe PMC text mining. Sharing a sentence is not in itself a finding about the gene and the disease. The quoted sentences say what the papers report.
hepatocellular carcinoma (35 papers, 2008 to 2025). A malignant tumor that arises from hepatocytes. "MAT2A is implicated in various human cancers, including hepatocellular carcinoma, and gastric cancer." (PMID 33138667, 2020). "Down-regulation of the liver-specific MAT1A gene encoding isozymes MATI/III and up-regulation of the MAT2A gene encoding isozyme MATII occur in hepatocellular carcinoma, and the resulting MAT1A: MAT2A switch leads to a decrease in SAM level." (PMID 33109235, 2020). "In T cells, both SAM and MTA levels impact methylation status, with elevated concentrations of either leading to T cell deficiency, and restricting MAT2A in T cells can enhance their activity within the hepatocellular carcinoma microenvironment, thereby inhibiting tumor growth." (PMID 39983717, 2025). "Various trans-activating factors such as Sp1, c-Mybl2, NF-kB, and AP-1 participate in MAT2A transcriptional upregulation in hepatocellular carcinoma (HCC)." (PMID 39353892, 2024). "The enhanced expression and activity of MAT2A results in an elevated production of SAM and has been associated with tumour progression in liver cancer, hepatocellular carcinoma (HCC) and colorectal cancer." (PMID 37795443, 2023). "miR-21-3p targets down-regulation of MAT2A and inhibits cell growth in hepatoma (Lo, Tsai & Chen, 2013)." (PMID 28316886, 2017). "In human hepatocellular carcinoma mat2A and mat2B genes are upregulated, highlighting the importance of the MATα2β complex in liver disease." (PMID 25075345, 2014). "Recent research has also found that the deletion of MAT2A mediated by CRISPR–Cas9 restricted the growth of hepatocellular carcinoma in mice by inhibiting T-cell exhaustion, which may be a potential strategy to enhance the ICI response of HCC." (PMID 40574864, 2025). "Moreover, SNHG6 sponges miR-1297 to increase MAT2A expression, upregulating MAT2A expression in hepatocellular carcinoma." (PMID 33859998, 2021). "Additionally, MAT2A cross-talks with polyamine synthesis in colon and liver carcinoma, and the sumoylated Matα2 protein protects human colon and liver cancer cells from apoptosis by regulating BCL2 expression." (PMID 31234428, 2019). "Most of the hepatic diseases studied to date, including cirrhosis, hepatocellular carcinoma or acute liver injury, concur with a reduction in AdoMet concentrations due to a decrease in Mat1a expression and the concomitant increase in that of Mat2a and Mat2b." (PMID 27548429, 2016). "NF-κB activation is required for the induction of MAT2A by TNF-α in hepatoma cells." (PMID 26418898, 2016). "Elevated levels of MTA and SAMe are tightly linked to T-cell exhaustion in hepatocellular carcinoma (HCC), and deletion of a key SAMe-producing enzyme MAT2A results in inhibition of T-cell exhaustion and limitation of HCC growth in mice." (PMID 37772039, 2023). "While MAT2A is a marker for rapid liver growth and dedifferentiation, which is transcriptionally induced in hepatocellular carcinoma (HCC)." (PMID 35292092, 2022). "Moreover, in human hepatoma cell lines, hypoxia induces genomic DNA demethylation through the direct activation of Methionine adenosyltransferase 2A (MAT2A) that maintains the S-adenosylmethionine (SAM)/S-adenosylhomocysteine (SAH) ratio, a critical marker of genomic methylation status." (PMID 26869355, 2016). "Development of liver cirrhosis and hepatocellular carcinoma (HCC) induces a switch in the expression of the isoenzymes in which MAT1A (encoding α1) expression is reduced and that of MAT2A increased." (PMID 23189196, 2012). "PDRG1 was found to interact with MAT2A protein to translocate into the nuclei in cell lines, including CHO (Chinese hamster ovary), COS-7 (monkey kidney), H35 (rat hepatoma), N2a (mouse neuroblastoma) and HEK-293T (human kidney)." (PMID 37240447, 2023). "In hepatocellular carcinoma, the dominant isoform MAT1A is downregulated while the extrahepatic isoform MAT2A is highly expressed." (PMID 36371321, 2022).
hepatocellular carcinoma (continued). "Alterations of methionine cycle in steatohepatitis, cirrhosis, and hepatocellular carcinoma induce MAT1A decrease and MAT2A increase expressions with the consequent decrease of S-adenosyl-L-methionine (SAM)." (PMID 35159219, 2022). "The conversion of key enzymes of methionine metabolism methionine adenosyltransferase (MAT) 1 A and MAT2A/MAT2B is closely related to fibrosis and hepatocellular carcinoma." (PMID 33273451, 2020). "In cancer research, MAT1A has been mostly described in the context of hepatocellular carcinoma (HCC), where it was previously shown that a switch in gene expression from MAT1A to MAT2A (M1-M2 switch) promoted cancer invasion and metastasis." (PMID 31600961, 2019). "NF-κB and AP-1 are required for basal MAT2A expression and the tumor necrosis factor-α (TNF-α)-induced transactivation of MAT2A in human hepatoma cells." (PMID 26418898, 2016). "Interestingly, repression of Mat1a with the induction of Mat2a, which is usually only expressed during liver development, is characteristic of NAFLD and aggressive hepatocellular carcinoma progression." (PMID 32908189, 2020). "The lack of significant changes in Mat1a or Mat2a expression in our silenced clones do not exclude the possibility that total suppression of Pdrg1 expression enhances MAT levels and, in turn AdoMet concentrations, known to be pro-apoptotic in hepatoma cells." (PMID 27548429, 2016).
liver cancer (17 papers, 2008 to 2025). An epithelial or non-epithelial malignant neoplasm that arises from the liver. "Moreover, the expression of the regulatory subunit MAT2B is frequently linked to the increase in MAT2A, conferring growth advantage to liver cancer cells and potentially serving as biomarkers." (PMID 39941901, 2025). "The increased expression of MAT2A (methionine adenosyltransferase 2A gene) in various cancers, including liver cancer, CRC, and gastric cancer, is recognized as a therapeutic target due to its role in regulating cell growth." (PMID 40574864, 2025). "As occurs in liver cancers, MAT2A expression appears increased in tamoxifen-resistant human breast cancers and in the TAMR-MCF-7 cell line, both compared with the tamoxifen-responsive versions." (PMID 39941901, 2025). "Further pharmacological screening identified a GSK3 inhibitor that selectively kills MAT2A-inhibited senescent liver cancer cells, suggesting a potential combination therapy between MAT2A and GSK3 inhibitors." (PMID 39239102, 2024). "MiR-203 expression is genetically regulated and contributes to patients’ outcomes and MiR-203 transfection in liver cancer cells targets the 3′-UTR of MAT2A and MAT2B genes and strongly inhibits their expression." (PMID 35159219, 2022). "High expression level of MAT2A in liver cancer, breast cancer, cervical squamous cell carcinoma, and gastric cancer was significantly associated with poor outcomes." (PMID 35729157, 2022). "MAT2B encodes for a regulatory subunit that controls the activity of the MAT2A-encoded isoenzyme and is induced in parallel to MAT2A in CRC and liver cancer." (PMID 29108270, 2017). "The protein expression level of MAT2A is decreased in renal cell carcinoma compared to normal tissues, while MAT2A is over-expressed in various gastrointestinal cancers, such as gastric cancer, colon cancer and liver cancer." (PMID 28316886, 2017). "As mentioned in the literature, a switch in gene expression from MAT1A to MAT2A, known as the MAT1A:MAT2A switch, has been found in liver cancer." (PMID 24098708, 2013). "Leptin has a mitogenic potential in liver cancer cells, which is mediated through the induction of Mat2a and Mat2b genes." (PMID 20808936, 2010). "Further research discovered that expression of MAT2A not only correlated with liver cancer cell proliferation but also was necessary for this process." (PMID 19025580, 2008). "In liver cancers, including HCC and cholangiocarcinoma, MAT1A expression and activity has been found to be reduced correlating with depletion of SAMe levels, promoter methylation status and, also, associates with MAT2A induction." (PMID 39941901, 2025). "Using the GeneMANIA prediction server and HPA, we discovered that SP1 could interact with MAT2A, and the complex may translocate into the nuclei in liver cancer." (PMID 37240447, 2023). "In liver cancer, the up-regulation of MAT2A occurs via transcriptional activation." (PMID 26418898, 2016). "We hypothesized that MAT2A and MAT2β may influence growth of liver cancer independently, this is the reason why we want to construct the dual small interfering RNA expression system targeting to MAT2A and MAT2β simultaneously." (PMID 19025580, 2008). "Switching from MAT1A to MAT2A expression could contribute to the development of liver cancer." (PMID 26418898, 2016). "MiR-203 transfection of HepG2 and Huh7 liver cancer cells targets the 3′-UTR of MAT2A and MAT2B and strongly inhibits the expression of MAT2A and MAT2B mRNAs and MATα2 and MATβ2 proteins." (PMID 31234428, 2019). "Although MAT2A function are well known in liver cancer, there has been no reports on its role in breast cancer." (PMID 26418898, 2016).
breast carcinoma (14 papers, 2016 to 2025). "Taken together, high C/N ratio of MAT2A in the tumorous tissues of breast cancer patients is associated with poor prognosis that is independent of age, ER, and tumor-node-metastasis (TNM) stages." (PMID 34065390, 2021). "MAT2A protein was found in the nucleus, where it can interact with chromatin-associated proteins, and subcellular localization of MAT2A protein was found to be an independently prognostic marker for breast cancer." (PMID 37240447, 2023). "The cause of increased MAT2A expression in breast cancer cells is of interest." (PMID 34065390, 2021). "However, higher mRNA expression of MAT2A was significantly associated with poor survival in breast cancer patients (p = 0.0057)." (PMID 34065390, 2021). "MAT2A dependency was also found for other lineages including breast cancer, pancreatic cancer, and Ewing sarcoma." (PMID 40015640, 2025). "High expression levels of MAT2A are also observed in colorectal cancer, leukemia, lymphoma, nasopharyngeal carcinoma, melanoma, ovarian carcinoma, prostate adenocarcinoma and breast cancer than in their corresponding normal tissues." (PMID 39872059, 2023). "We have demonstrated that subcellular localization of MAT2A protein is an independent prognostic marker for breast cancer." (PMID 37240447, 2023). "Previous studies on MAT2A translocation and its relevance to breast cancer survival inspired us to explore the prognostic potential and the clinical application of the subcellular localization of MAT2A in our LIHC cohort study." (PMID 37240447, 2023). "Breast cancer patients with a higher cytoplasmic to nuclear expression ratio (C/N) of MAT2A protein had lower 5-year survival rates than those with lower C/N ratios." (PMID 37240447, 2023). "We also discovered that subcellular localization of the MAT2A protein has independently prognostic relevance in breast cancer patients." (PMID 37240447, 2023). "Accumulating evidence suggested that SAM and its enzyme MAT2A are closed related with tumorigenesis of various cancers, like colon and breast cancers." (PMID 36891236, 2023). "The GNMT and MAT1A protein expressions and the C/N ratio of MAT2A were also correlated with the five-year relative survival rate in our breast cancer cohort." (PMID 34065390, 2021). "We successfully demonstrated that the subcellular distribution (C/N ratio) of a key methionine cycle enzyme, MAT2A, can predict a poorer survival in breast cancer patients." (PMID 34065390, 2021). "Our study is the first one to investigate the clinical prognosis potential of MAT2A in breast cancer." (PMID 34065390, 2021). "In vitro studies found that breast cancer cell lines with a higher MAT2A C/N ratio were more invasive." (PMID 34065390, 2021). "Using the GEPIA, a poorer breast cancer survival was observed in patients with higher MAT2A mRNA level, suggesting a potential role of MAT2A in breast cancer development." (PMID 34065390, 2021). "A MAT2A immunoreactivity was observed in the cytoplasm and nuclei in the breast cancer and adjacent normal tissue." (PMID 34065390, 2021). "GNMT, MAT1A, MAT2A-biomarker IHC panel was compared with the clinical survival record in breast cancer patients, to examine the accuracy of IHC-based methods for identifying clinical prognosis." (PMID 34065390, 2021). "Although the case number is limited, we showed that MAT2A immunoreactivity was significantly higher in TAM-resistant cases of human breast cancer than in TAM-sensitive cases." (PMID 26418898, 2016). "Immunohistochemistry confirmed that MAT2A expression in TAM-resistant human breast cancer tissues was higher than that in TAM-responsive cases." (PMID 26418898, 2016). "Furthermore, subcellular localization of MAT2A protein was found to have prognostic application in breast cancer patients." (PMID 37240447, 2023). "Furthermore, it is noteworthy that high C/N ratio (>1) of MAT2A protein expression was present in more than 50% of the breast cancer specimens in our cohort." (PMID 34065390, 2021).